CD4 (CD4 molecule)
Diseases named in the same sentence as CD4 in open-access papers (continued):
Sharing a sentence is not in itself a finding about the gene and the disease.
infection (continued). "All together, these results imply that compared to infection-naïve individuals, convalescents’ spike-specific CD4+ T cells may be superior in surviving and migrating to the respiratory tract." (PMID 34636722, 2021). "Importantly, during the course of infection, Mtb adapts to the changing environment of the host, and it is poorly described how differential in vivo antigen expression influences CD4 T cell responses and vaccine potential." (PMID 33879592, 2021). "Furthermore, it was determined that CCL5 was upregulated in vaginal tissue following immunisation and that CCL5 was required to retain CD4+ TRMs at the site of infection." (PMID 33668777, 2021). "Heterogeneity in the exhausted CD4+ T cell population has been observed as some subsets of CD4+ T cells are able to persist throughout infection while others are functionally diminished early in the course of infection." (PMID 34696381, 2021). "Furthermore, we demonstrated that trans infection of total CD4+ T cells can be inhibited by treatment with anti-DC-SIGN MAb." (PMID 33688006, 2021). "We previously showed in vitro and ex vivo that human colonic CD11c+, DC-SIGN+, CCR5+ DCs can extend dendrites containing HIV-1 to epithelial cells, as well as retract them, and thus transfer infection to CD4+ T cells: a clear proof of principle of an HIV-1-DC uptake mechanism in the gut8." (PMID 34253821, 2021). "These cells might get infected and disseminate infection further to lymph nodes, where even more CD4+ cells can be infected." (PMID 33659876, 2021). "Additionally, female gender possesses better immunovirological parameters, which is higher CD4 + T cells following primary HIV‐1 infection at the beginning of infection compared to males." (PMID 34400726, 2021). "In addition, CD4 T cells play a critical role in regulating long-term infection by providing CD8 T cell help, in part via CD40L activation of antigen-presenting cells." (PMID 34586873, 2021). "In addition, caspase-3/7+ apoptosis was not enhanced by either R5 or X4 HIV-1, but rather repressed in naïve CD4+ T cells when compared with that for mock infection." (PMID 33924786, 2021). "Finally, we describe the control exerted by CD4 T cells during latency to prevent reactivation and re-infection." (PMID 34959486, 2021). "High levels of genital inflammation have been observed in a well-characterized cohort of South African females and high levels of inflammation during early infection in this cohort correlated with VL set-point and, to a lesser degree, disease progression (as measured by CD4 depletion)." (PMID 34344423, 2021). "Similarly, we reported that gene expression patterns in purified blood CD4 T cells during infection were correlated with clinical disease severity." (PMID 33632195, 2021). "The two animals that succumbed to infection exhibited the lowest CD4+ T cell count, suggesting that these cells may play a role in the immune protection offered by VSV-EBOV." (PMID 34578125, 2021). "Moreover, one of the significant roles of NK cells and CD4+ T lymphocytes in liver protection and infection control is interferon-gamma production (IFN-γ)." (PMID 34578107, 2021). "Microglia/macrophage interaction with CD4+ T cells is critical in the efficient transition from an innate immune response prevalent during the acute phase to a chronic-adaptive inflammatory response observed during the chronic phase of RSA59 infection." (PMID 34898656, 2021). "Both preexisting CD8+ and CD4+ T cells have been associated with reduced symptoms and viral shedding after infection in humans and in a non-human primate challenge study." (PMID 34372607, 2021). "Although mice depleted of CD4+ T cells were unable to eliminate C. neoformans Δsgl1 from the lungs, they showed no signs of morbidity or fungal dissemination and were fully protected against WT infection during which time they clear the mutant strain." (PMID 34568097, 2021).
infection (continued). "Moreover, ARV fails to target lymphatic system cells (e.g., dendritic cells and macrophages) involved in virus transmission to helper T lymphocytes (CD4+ T cells), resulting in post-treatment infection relapse." (PMID 34452255, 2021). "This indicates that cathepsin B activity reduces the susceptibility of target cells to CD4-independent infection while not affecting CD4-dependent infection." (PMID 34421929, 2021). "However, our data suggest that Mtb glycolipids potentially impair or enhance HIV-1 trans-infection, where DCs capture and present virus to CD4 T cells, with important implications for virus transmission and dissemination." (PMID 33669411, 2021). "Thus, limiting the number of α4β7+ CD4+ T cells that traffic to that region will offer some level of protection from infection—a reduction that is implicitly captured by the protection mechanism." (PMID 34106916, 2021). "Thus, our data suggest that ZIKVBR infection suppresses CD8 T cell immunity despite inducing a numerically equivalent CD4 T cell response in the blood." (PMID 34193875, 2021). "In the survival analysis to determine the impact of triple infection on disease progression, time to the achievement of CD4+ T-cell counts ≤ 350 cells/μl was significantly shorter in the triple infection group than in the single and double infection groups (P < 0.05)." (PMID 32038599, 2020). "Despite this, less is known about CD4+ TRM cells in infection settings, in comparison to their CD8+ TRM cell counterparts, or whether CD4+ TRM cells form effector TH cell subtypes, such as TH1, TH2, and TH17, or even TFH cells." (PMID 32858901, 2020). "Nevertheless, only limited subsets of memory CD4+ T cells supported productive infection." (PMID 32353080, 2020). "Overall, knowledge about CD4+ T cell response after infection or vaccination is limited." (PMID 32806696, 2020). "Th2 and Th1 populations at the cellular level could only reflect a part of CD4+T cell immune response to the infection." (PMID 33005098, 2020). "In addition to the quantification of p24, we sorted the gag tagged CD4+ T cells 12 days post-infection with TF and NT viruses for the determination of IFN-α resistance." (PMID 32066770, 2020). "Overall, our data suggested that Envs’ ability to infect CD4+ cells, either directly or indirectly via trans-infection, does not advantage variants during transmission." (PMID 31978062, 2020). "The CD4+ T cells can be activated by infection and will develop to effective T cells." (PMID 32670257, 2020). "Thus, SIV is seeded in CD4 T cells from all the tissues analyzed in RMs treated with ART at week 6 post infection." (PMID 31723251, 2020). "The CD4+ T cell is also likely to be key to adaptive immune memory to STH infections." (PMID 32655568, 2020). "However, many immunoregulatory molecules and pathways, most notably those associated with interleukin-10 (IL-10) production, are activated following infection, which can suppress anti-parasitic CD4+ T cell functions." (PMID 32101732, 2020). "Finally, we measured the frequency of resting CD4+ T-cell infection by the quantitative viral outgrowth assay at the same time points as rca-RNA measurements." (PMID 32198428, 2020). "Additionally, poor CD4 recovery is more likely to occur in patients who initiate ART late in the course of infection." (PMID 32949118, 2020). "We previously showed that while wildtype (WT) mice develop mild disease and survive infection with lymphocytic choriomeningitis virus (LCMV), LCMV infection of STAT1-deficient mice results in a lethal wasting disease that is dependent on IFN-I and CD4+ cells." (PMID 32310998, 2020). "Contrastingly, the infection with members of Enterovirus C types in HIV-positive participants was independently associated with a higher CD4+ T cell count compared to PLHIV not infected with enteroviruses." (PMID 32079128, 2020).
infection (continued). "Interestingly, while all three strains of mice showed reduced CD4 T cell numbers following infection with S. Typhimurium, infected iNOS−/− and IFN-γ−/− mice also had reduction in CD8 T cell numbers." (PMID 32269573, 2020). "Similarly, infection with H. bakeri results in protection against N. brasiliensis infection via IL-33-dependent induction of IL-5+CD4+ T cells capable of recruiting activated eosinophils to the lung." (PMID 32655568, 2020). "Similarly, T regs were also detected from lesions of L. major-infected C57BL/6 mice and they responded to L. major antigen and accumulate rapidly at the site of infection and suppress other CD4+ T cell activity, which favors parasite persistence." (PMID 32656269, 2020). "In addition, higher frequencies of regulatory CD4+FoxP3+ T cells are observed in C3H/HeN compared to C57BL/6 mice in the infection with R. conorii." (PMID 33091016, 2020). "The viral reservoir marks an important mechanism by which inflammation can persist; in lymphoid tissue, HIV-1 productive infection in a small percentage of permissive cells can result in abortive infection of bystander cells (>95% CD4+ T lymphocyte population)." (PMID 32155980, 2020). "(B) GFP expression in primary CD4+ T-cells after infection with V1/shLuc or V1/shCCDC137." (PMID 32538781, 2020). "Identification of the specific antigens recognized by CD4+ T cells following the development of resistance under a trickle infection may provide a fertile avenue for the discovery of novel vaccine candidates." (PMID 32655568, 2020). "However, in both Batf3−/− and wild-type mice, CD4 memory T cells contributed to the protection of mice after challenge with lethal infection." (PMID 32669460, 2020). "Lastly, to determine whether pre-infection α4β7 expression was associated with HIV disease progression, cases of PWID were examined for time to CD4+ T cell count of 200 cells/μL." (PMID 33166790, 2020). "Infection of activated CD4+ T cells usually results in cell death; however, when infected cells survive long enough, they revert to a resting memory state, estimated at 0.01–100 per 106 CD4+ T cells, with minimal proviral gene expression." (PMID 33334019, 2020). "An HIV-positive individual may transition through various stages of infection (categories 1 to 3 and A, B and C) based on the CD4+ count and presence of comorbid conditions." (PMID 32129664, 2020). "Healthier HIV infected MSM, as reflected from a higher CD4 count at diagnosis, may be unaware of his infection and could have maintained their activity in sex networking thereby supporting ongoing transmission." (PMID 31997717, 2020). "It is unclear whether live oral attenuated typhoid vaccine, Ty21a, could elicit and generate antigen-specific CD4+TRM responses in the human terminal ileum (TI) (site of infection for S. Typhi)." (PMID 32098623, 2020). "Trans-infection of latently infected CD4+ T cells could thus result in reactivation of HIV-1 by activation of the TCR with concomitant TLR8 signaling from endosomal degradation of virus particles." (PMID 31919342, 2020). "The administration of calnexin in glucan particles elicited calnexin-specific CD4+ T cells, and vaccinated mice demonstrated resistance to infection by Blastomyces dermatitidis, Histoplasma capsulatum, Pseudogymnoascus (Geomyces) destructans, Fonsecaea pedrosoi, and A. fumigatus." (PMID 32722452, 2020). "One had a very low CD4 count indicative of a long‐established infection." (PMID 31821698, 2020). "Importantly, we further investigated miR-27a/b status in OLP cell models by employing LPS treatment to mimic infection conditions in HOKs or adopting activated CD4+ T cell supernatants to simulate the microenvironment of autoimmune response." (PMID 31942011, 2020).
infection (continued). "CD4+ T cells are critical drivers of inflammatory responses during infections and as they progress from a naïve to activated state, the metabolic pathways they use have to change to meet the new energy demands required to proliferate and produce effector molecules." (PMID 33049000, 2020). "We demonstrate that lowered mTOR activity in effector CD4+ T cells during the course of Plasmodium yoelii nonlethal (PyNL) infection correlates with the temporal loss of T-bet expression." (PMID 32817333, 2020). "Though these interactions may have some role in virus association with specific cells, CD4 and the co-receptor molecules CCR5 and CXCR4 remain the key receptors involved in viral fusion and cellular infection." (PMID 31863725, 2020). "However, vaccination of mice with Msm ΔespG3::mtp64 prior to Mav infection was found to increase the frequencies of IL-17-producing Th17, Tc17 as well as IFNγ/IL-17 double-producing CD4+ and CD8+ T cells." (PMID 32582196, 2020). "We found that TF Envs were not significantly better than CI clones at mediating CD4+ dependent TZM-bl entry, DC-SIGN binding and trans-infection of CD4+ cells, confirming results of a previous study that also used matched TF and CI PSV albeit from subtype B variants." (PMID 31978062, 2020). "HVEM and its binding partners promote IFN-γ-producing CD4+ T cells in the DLNs following infection." (PMID 32398314, 2020). "The present study showed that symptomatic infections were associated with decreased proportions and absolute counts of total CD3 + T cells, CD4 + and CD8 + T cells, CD19 + B cells, and CD11c + cells compared to asymptomatic infections, corroborating previously reported data." (PMID 33036624, 2020). "In order to follow antigen-specific T cells, Ly5.1+ TCR transgenic CD8+ and CD4+ T cells specific for the immuno-dominant gp33 (P14) or gp61 (Smarta) peptides were transferred into wild-type (WT) C57BL/6 mice prior to LCMV clone 13 infection." (PMID 32152316, 2020). "Thus, further investigations are needed to characterize the type of CD4+ T-cells, which is responsible for neutrophil infiltration induced by prior infection of Mp in DBA/2 mice." (PMID 33520736, 2020). "HIV-1-specific CD4 T cells expand at high frequency during the early phase of the infection." (PMID 32714330, 2020). "Furthermore, circulating CD4 and CD8 T-cell responses were not significantly different between vaccine groups for either CD4 or CD8 T-cells during either acute or early set point phases of infection after challenge." (PMID 32820216, 2020). "Further, levels of these S reactive CD4+ T cells can modulate outcome of infection with CoV2." (PMID 33133083, 2020). "Despite this noted contraction of CD4+ T lymphocytes, the functionality of these cells does not appear to be impaired, since we observed an increase of CD38+CD4+ T cells in LbAgS cell cultures from BT and DT patients, indicating an activation profile of CD4+ T cells in patients presenting infection." (PMID 32203546, 2020). "Increased tryptophan catabolism may enable the survival of Mtb at the site of infection by modulating CD4+ T cell responses, inducing immune tolerance and bacterial persistence, and could also protect the host from excessive inflammation." (PMID 33266347, 2020). "Therefore, NK cells produce most of the local CNS IFN-γ early in the course of infection, but at later times, CD4+, and especially CD8+, T cells become the predominant source." (PMID 31963302, 2020). "However, successful response to infection is followed by marked increase in the T CD4+:Treg cell ratio and this is due mostly to the higher number of T CD4+." (PMID 32051758, 2020). "One possible reason might be that during infection a strong and durable HCV-specific CD4+ and CD8+ T cell response is associated with a spontaneous clearance of the HCV infection." (PMID 33262767, 2020).
infection (continued). "Notably, tissue damage was also observed in C-IRIS-induced mice with Ifng–/– CD4+ T cells, but to a lesser extent in mice with infection only." (PMID 33133067, 2020). "Fewer CD4+ T cells in the blood were also observed at 48 h after infection." (PMID 32850501, 2020). "However, both transmission probability and disease-related mortality are dependent on within-host viral loads and CD4 level and hence greatly affect the estimation of new infections." (PMID 32532238, 2020). "Upon infection, the priming of CD4+ T cells in lymphoid organs is delayed." (PMID 33105734, 2020). "In spite of our result, the role of CXCR3 in CD4+ T cells migration has been shown in infection by Plasmodium chabaudi, however, in our model we believe that others chemokine might be involved in CD4+ T cells migration to spleen." (PMID 32574175, 2020). "The twelve animals were of the same species, infected with the same virus, same infectious dose, same infection route, in a similar environment, and CD4 + T cells from blood and LN were isolated in exactly the same way and at the same timepoints as the AGM and MAC in the current study." (PMID 33298174, 2020). "In the future, a Cox regression model could be made to study whether the number of IFN-γ+CD4+ T cells is a good predictor of time to death for CRO infection." (PMID 33072617, 2020). "Although the vaccine was able to generate both HCMV-specific CD8+ and CD4+ T-cell response, the immunity induced by vaccination did not prevent secondary infection in pregnant women, while mucosal immunity induced by natural infection did." (PMID 32397070, 2020). "Our data further suggests that altered metabolic function of activated CD4+ T cells isolated from early lactation cows may contribute to altered immune responsiveness of these cows to infection, as a result of reduced function of their activated CD4+ T cells." (PMID 32132555, 2020). "Since chronic AE, other than early AE, is associated with severe depletion of T-cells after 6 weeks of infection, we investigated the dynamics of host CD4+ T-cell responses during experimental secondary AE for up to 7 weeks (42 days) post infection; i.e., up to the chronic phase of the disease." (PMID 32457746, 2020). "However, it has been shown that following an infection with PRRSV an increase in T-bet+ CD4+ T cells can be observed." (PMID 33013937, 2020). "We observed a trend toward increased CD4+ RTEs in VNPs compared to SN individuals (p = 0.0813) despite an extended duration of infection, suggesting a role for increased thymic output in the maintenance of the naive CD4+ T cell compartment and CD4+ T cell pool within these individuals." (PMID 32194543, 2020). "CD4+ αβ T-cells are key mediators of the immune response to a first Plasmodium infection, undergoing extensive activation and splenic expansion during the acute phase of an infection." (PMID 33329568, 2020). "We speculate that this IFN-γ production is driven by endogenous CD4+ T cells, as had been previously shown to be the case following pulmonary C. muridarum infection in neonatal mice and intravaginal infection with C. muridarum." (PMID 32184237, 2020). "IL-22 belongs to the IL-10 cytokine family and is produced in the intestinal mucosa by group 3 innate lymphoid cells (ILC3s; produces IL-22 during the early stage of infection) and CD4 + T cells (including Th17 cells and Th22 cells; produces IL-22 during late stage of infection)." (PMID 32082288, 2020). "Nevertheless, the role of ICOS in the formation of memory CD4+ T cells appears to be context-dependent and could be influenced by the length of the infection." (PMID 32348365, 2020). "Another conceivable cause of reduced DPP4+ T cell frequencies might lie in the early infection and destruction of memory/helper T cells expressing the CD4+CD45RO+CD26+ phenotype." (PMID 32946499, 2020).